ELAVL2 (ELAV like RNA binding protein 2)
Description:
RNA-binding protein that binds to the 3' untranslated region (3'UTR) of target mRNAs (By similarity). Seems to recognize a GAAA motif (By similarity). Can bind to its own 3'UTR, the FOS 3'UTR and the ID 3'UTR (By similarity).
Synonyms: HuB; HEL-N1; HELN1
Tractability: PROTAC: ubiquitination databases record sites on it; its protein half-life has been measured.
Gene: Protein-coding gene on chromosome 9 (23,690,099 to 23,826,352, reverse strand). Ensembl gene ENSG00000107105.
Subcellular location (Human Protein Atlas): Nucleoplasm; Cytosol
Pathways (Reactome):
Disease: Dengue Virus-Host Interactions
Gene Ontology:
Molecular function: protein binding; RNA binding; mRNA 3'-UTR binding; protein-RNA adaptor activity; nucleic acid binding
Biological process: regulation of DNA-templated transcription
Cellular component: nucleoplasm; ribonucleoprotein complex
Genetic constraint (gnomAD): Loss-of-function variants: 4 observed, 36.73 expected, observed/expected ratio (o/e) 0.11, 90% interval 0.053 to 0.25. The upper end of that interval is the gene's LOEUF score, 0.25, which puts it in group 1 of 6, group 1 being the genes least tolerant of losing a copy. Missense variants: 432 observed, 465.21 expected, observed/expected ratio (o/e) 0.93, 90% interval 0.86 to 1.01. Synonymous variants: 193 observed, 163.13 expected, observed/expected ratio (o/e) 1.18, 90% interval 1.05 to 1.33.
Homologues: Orthologues: chimpanzee ELAVL2 (100% identical), dog ELAVL2 (100% identical), macaque ELAVL2 (100% identical), pig ELAVL2 (100% identical), rabbit ELAVL2 (100% identical), guinea pig ELAVL2 (99% identical), mouse Elavl2 (99% identical), rat Elavl2 (99% identical), tropical clawed frog elavl2 (96% identical), zebrafish elavl2 (91% identical), Drosophila melanogaster Rbp9 (62% identical), Drosophila melanogaster fne (59% identical). Paralogues in human: ELAVL4 (90% identical), ELAVL3 (82% identical), ELAVL1 (67% identical), RBMS3 (30% identical), RBMS1 (29% identical), RBMS2 (28% identical), PABPC1L (25% identical), PABPC1 (24% identical), PABPC3 (23% identical), SF3B4 (23% identical), PABPC4 (23% identical), SYNCRIP (23% identical), and 12 more.
Diseases named in the same sentence as ELAVL2 in open-access papers:
ELAVL2 is named in the same sentence as 70 diseases in open-access papers, as found by Europe PMC text mining. Sharing a sentence is not in itself a finding about the gene and the disease. The quoted sentences say what the papers report.
schizophrenia (9 papers, 2011 to 2025). A major psychotic disorder characterized by abnormalities in the perception or expression of reality. "Genome-wide association studies (GWAS) have identified ELAVl2 as a key gene in schizophrenia development through family screenings and genotyping." (PMID 40000387, 2025). "For example, ELAVL2 has been linked to learning and memory formation, autism spectrum disorder and schizophrenia; ELAVL3 has been linked to amyotrophic lateral sclerosis (ALS) and cerebellar ataxia; ELAVL4 has been linked to AD and PD." (PMID 39425207, 2024). "Genome-wide association studies indicate significance for the SNP in the ELAVL2 gene associated with schizophrenia." (PMID 24564241, 2013). "Elavl2 (SNP ID, rs10491817) is associated with schizophrenia, particularly in Asian populations." (PMID 30687010, 2018). "The identification of ELAVL2 as a susceptibility gene for schizophrenia in both Japanese and Chinese cohorts led us to examine whether the expression levels of the gene are altered in the postmortem brains of patients with schizophrenia." (PMID 21674006, 2011). "In stage III, we scrutinized the ELAVL2 gene by genotyping gene-centric tagSNPs in the third sample set of 293 family samples (1,163 individuals) of Chinese descent and the SNP in the gene showed a nominal association with schizophrenia in Chinese population (p = 0.026)." (PMID 21674006, 2011). "It is noted that ELAVL2 has connections to three reference nodes and was reported as schizophrenia-related gene in recent GWAS." (PMID 27510319, 2016). "In summary, we provided a suggestive evidence for the contribution of ELAVL2 to the pathogenesis of schizophrenia, in both Japanese and Chinese populations." (PMID 21674006, 2011). "Moreover, Elavl2 interacts with GABAB receptors at both RNA and protein levels, participating in signal transduction ELAVl2 has also been implicated in neurological disorders, including schizophrenia and autism." (PMID 40000387, 2025). "Defects in ELAVL2/HuB, ELAVL4/HuD, and their target transcripts can lead to abnormal neuronal proliferation and development and result in the pathogenesis of numerous CNS disorders, including seizures, autism, and schizophrenia." (PMID 36438188, 2022).
autism (5 papers, 2015 to 2025). Persistent deficits in social interaction and communication and interaction as well as a markedly restricted repertoire of activity and interest as well as repetitive patterns of behavior. "Elavl2, primarily expressed in the nervous and reproductive systems, is critical for central nervous system and retinal development; its dysregulation has been implicated in neurodevelopmental disorders such as autism." (PMID 40000387, 2025). "Regulation of transcript expression by ELAVL2 has been shown to be critical for neuronal function and clinically relevant to autism, and ELAV1/HUR and ELAV2/HUB are critical for the occurrence of MMP-9 mRNA stabilization upon neuronal activation." (PMID 36005139, 2022).
lung carcinoma (4 papers, 2013 to 2025). "Among mutated genes, we noticed that MUC2 and ELAVL2 are two genes that were significantly mutated in BrM samples as compared to primary lung cancers." (PMID 39593114, 2024). "Proteins of the ELAV gene family (Hu genes) such as ELAVL2 are tumor antigens that are investigated for early stage lung cancer detection." (PMID 24379827, 2013). "Also, proteins of the ELAV gene family (Hu genes) such as ELAVL2 are tumor antigens that are investigated for early stage lung cancer detection." (PMID 24379827, 2013). "At the same time, several genes downregulated in NPRL2−/− cells are also known to be downregulated in lung cancer (FBLN2, LBH, AMPH-1), glioblastoma (ELAVL2), and liver cancer (IGFBP4)." (PMID 41469472, 2025).
autism spectrum disorder (3 papers, 2018 to 2024). A spectrum of developmental disorders that includes autism, and Asperger syndrome. "Some studies report that ELAVL2-regulated pathways are involved in normal human brain function and their disruption may play a role in neurodevelopmental disorders such as autism spectrum disorder (ASD)." (PMID 34733151, 2021).
breast carcinoma (3 papers, 2019 to 2023). "The co-expression network revealed that ELAVL2, VIM, MRPS12, HSPE1, EZH2, HIST1H4B, and MRPL13 played a vital role in the progression of breast cancer, and we further selected important modules of target genes through MCODE." (PMID 30881302, 2019).
COVID-19 (3 papers, 2023 to 2024). A disease caused by infection with severe acute respiratory syndrome coronavirus 2. "Interestingly, ELAVL2-4 RBPs, predicted from our analysis to be SECReTE motif-associated RBPs, were also found to be deregulated in COVID-19 patients." (PMID 36814457, 2023).
major depression (3 papers, 2022 to 2026). "rs1021362 lies in SORCS3, a gene previously associated with stress response associated with MD, rs3793577 lies in ELAVL2, whose silencing in animal models is associated with reduced behavioral despair; the remaining GVs have been previously associated with major depression by several PheWAS studies." (PMID 35886042, 2022).
bipolar disorder (2 papers, 2011 to 2022). A disorder of the brain that causes unusual shifts in mood, energy, activity levels and the ability to carry out day-to-day tasks. "Furthermore, our research pinpointed two top loci—miR-2113/POUSF2 and LINC01239 ELAVL2—that were associated with increased bipolar-disorder risk and higher intelligence, suggesting a common underlying biological mechanism of these traits." (PMID 35286190, 2022). "For example, the lead SNP rs1487441-A allele at loci miR-2113/POUSF2 and the rs4977839-A allele at LINC01239/ELAVL2 associated with leadership position and a high level of managing demands were also found to be associated with an increased risk for bipolar disorder." (PMID 35286190, 2022). "Consistently, another top locus in the intergenic region at LINC01239/ELAVL2 on 9p21.3 in the present study has also been identified as a genome-wide significant locus for bipolar disorder." (PMID 35286190, 2022). "However, the experiments showed that the expression levels of ELAVL2 were not different among brains from schizophrenics, bipolar disorder patients and control subjects." (PMID 21674006, 2011).
brain tumor (2 papers, 2018 to 2020). "In brain tumor and non-small cell lung carcinoma cells, HuB (ELAVL2), the only neural ELAVL protein found to be expressed in cancer cells, was shown to initiate the cytoplasmic translocation of HuR." (PMID 32455577, 2020).
glioma (2 papers, 2022 to 2024). A benign or malignant brain and spinal cord tumor that arises from glial cells (astrocytes, oligodendrocytes, ependymal cells). "Furthermore, Kaplan–Meier survival analysis indicated that low expression of ELAVL2 is associated with dismal outcome in both glioma (p < 0.0001) and only GBM datasets (p = 0.01)." (PMID 38548861, 2024). "Taken together, these data indicate that the loss of ELAVL2 is associated with the histological and molecular features of glioma and thus may be used as a novel biomarker for the aggressiveness of gliomas." (PMID 38548861, 2024). "The CNA status and mRNA expression level of ELAVL2 were found to correlate with clinical and molecular features of glioma, and its loss was associated with aggressive MES transition and unfavorable survival rates of GBM patients at all genomic, mRNA, and protein levels." (PMID 38548861, 2024). "Taken together, these results show that the expression of ELAVL2 is negatively correlated with that of EMT-related molecules at both mRNA and protein levels, suggesting that the loss of ELAVL2 may promote glioma progression by facilitating MES transition." (PMID 38548861, 2024). "Importantly, glioma patients with high ELAVL2 protein expression levels are significantly associated with better survival than those with low expression, and the result remained significant when only GBM patients were analyzed." (PMID 38548861, 2024). "To further substantiate the prognostic role of ELAVL2 in glioma, we analyzed the protein expression level of ELAVL2 in 182 glioma patients with follow-up information across four TMA sets (TMA1573, 2248, 2249, 2758) using an anti-ELAVL2 antibody." (PMID 38548861, 2024). "Strikingly, only ELAVL2 was found to be aberrantly deleted at high frequency in glioma patients (12%)." (PMID 38548861, 2024). "Notably, the expression level of ELAVL2 was the lowest in tumors belonging to WHO grade IV compared to lower grade gliomas." (PMID 38548861, 2024). "Notably, overall survival of glioma patients was found to be affected by the ELAVL2 deletion status." (PMID 38548861, 2024). "Also, our findings regarding the deletion status of ELAVL2 and the subsequent alteration in mRNA expression levels may present a novel molecular pathway in glioma development and progression." (PMID 38548861, 2024). "In summary, our findings identify ELAVL2 as a critical tumor suppressor and mRNA stabilizer that regulates MES transition in GBM, underscoring its role in transcriptomic plasticity and glioma progression." (PMID 38548861, 2024). "Collectively, these data suggest that ELAVL2 depletion may represent a characteristic feature of GBM, with potential relevance to glioma progression." (PMID 38548861, 2024). "Furthermore, ELAVL2 was found to be deleted mostly in grade IV glioma, GBM, IDH-wt glioma, and GBMs of classical and MES molecular subtypes, all of which define the aggressive phenotypes of glioma." (PMID 38548861, 2024). "Furthermore, the expression level of ELAVL2 was low in gliomas with wild-type isocitrate dehydrogenase 1 (IDH1) gene, which plays a critical role in glioma progression." (PMID 38548861, 2024).
infertile (2 papers, 2021 to 2024). "For Mice lacking ELAVL2, are infertile and have follicle-free ovaries." (PMID 38654363, 2024).
ovarian carcinoma (2 papers, 2024). A malignant neoplasm originating from the surface ovarian epithelium. "The examination of individual mutations in hub genes has provided insights into the prevalence of alterations in ELAVL2, which exhibited the greatest frequency of 5% in ovarian cancer." (PMID 38654363, 2024). "The prognostic information of our five hub genes were determined using the KM plotter (SCN2A, ELAVL2, BCL2, MAF, and ZNF532,) to confirm the association between patterns of expression and metastasis risk in ovarian cancer patients." (PMID 38654363, 2024). "Resistance to Chemotherapy in ovarian cancer is a result of high ELAVL2 expression of protein in tumour cells that encourages tumour growth, invasion, and migration, disturbs the cell cycle, and blocks tumor cell apoptosis brought on by chemotherapeutic medicines through a variety of routes." (PMID 38654363, 2024). "The previous study observed a downregulation of the genes SCN2A, ELAVL2, ZNF532, MAF and BCL2 which were identified in ovarian cancer." (PMID 38654363, 2024). "Furthermore, it was recently reported that ELAVL2 and ELAVL4 activated glycolysis pathway under glucose deprivation condition and their high expression levels were responsible for the development of chemoresistance to paclitaxel in ovarian cancer cells." (PMID 38548861, 2024).
Parkinson’s (2 papers, 2017 to 2024). "On the other hand, PZP and ELAVL2 were known as pyramidal neuron-specific markers linked to Parkinson’s." (PMID 38735925, 2024).
Azoospermia (1 paper, 2023). Absence of any measurable level of sperm,whereby spermatozoa cannot be observed even after centrifugation of the semen pellet. "Testicular biopsies from patients with non-obstructive azoospermia, a severe cause of male infertility, were also examined for the relevance of ELAVL2 to this pathology." (PMID 37697079, 2023). "Single-cell transcriptome data revealed that ELAVL2 is enriched in spermatogonial cells but is reduced in non-obstructive azoospermia patients." (PMID 37697079, 2023).
colorectal cancer (1 paper, 2024). A primary or metastatic malignant neoplasm that affects the colon or rectum. "ELAVL1 (HuR), a homolog of ELAVL2, has recently been found to be significantly expressed in colorectal cancer and to have the ability to control the proliferation and migration of tumor cells." (PMID 38654363, 2024).
esophageal squamous cell carcinoma (1 paper, 2020). Esophageal squamous cell carcinoma (ESCC) is a type of esophageal carcinoma (EC) that can affect any part of the esophagus, but is usually located in the upper or middle third. "Therefore, the expression upregulation of ELAVL2 might result in abnormality in splicing and maturation of mRNA and regulation of gene expression play important role in esophageal squamous cell carcinoma." (PMID 32219019, 2020).
Hyperglycemia (1 paper, 2019). An increased concentration of glucose in the blood. "We correlate the diabetic state with hyperglycemia, lower body weight, presence of late thermal hypoalgesia, Elavl2 and Elavl3 downregulation, HuB upregulation, and HuD downregulation in comparison to control conditions." (PMID 31013625, 2019).
oligodendroglioma (1 paper, 2024). A well-differentiated (WHO grade II), diffusely infiltrating neuroglial tumor, typically located in the cerebral hemispheres. "Similarly, ELAVL2 expression level was low in the higher histopathological malignancies, being the lowest in GBM and highest in oligodendroglioma." (PMID 38548861, 2024).
ovarian insufficiency (1 paper, 2023). "There is accumulating evidence supporting the relevance of this gene family to later onset neurodegenerative diseases, but data is emerging also implicating these genes in neurodevelopmental disorders, and for ELAVL2, a potential link to primary ovarian insufficiency." (PMID 37697079, 2023).
prostate tumors (1 paper, 2019). "Elevated methylation of ELAVL2 was shown in high Gleason scores of prostate tumors." (PMID 30881302, 2019).
seminoma (1 paper, 2021). A radiosensitive malignant germ cell tumor found in the testis (especially undescended), and extragonadal sites (anterior mediastinum and pineal gland). "We also found that ELAVL2 is highly expressed in seminoma tissues and TCam‐2, a well‐recognized seminoma cell line." (PMID 34296486, 2021). "Third, ELAVL2 showed high expression in human seminoma tissue and TCam‐2 cell line that generated from pure seminoma." (PMID 34296486, 2021).
small cell lung carcinoma (1 paper, 2022). Small cell lung cancer (SCLC) is a highly aggressive malignant neoplasm, accounting for 10-15% of lung cancer cases, characterized byrapid growth, and early metastasis. "The three other family members, ELAVL2, ELAVL3 and ELAVL4, initially received much attention as neuroendocrine markers for small cell lung cancer (SCLC)." (PMID 35465324, 2022).
teratocarcinoma (1 paper, 2021). A germ cell tumor characterized by the presence of an embryonal carcinoma component and a teratoma component. "Former studies revealed that ELAVL2 promotes translation of targeting mRNAs containing AU‐rich elements by accelerating the formation of translation initiation complexes, like GLUT1 in adipocytes, DDX6 in oocytes, and neurofilament M in human teratocarcinoma cells." (PMID 34296486, 2021).
testicular cancer (1 paper, 2021). A primary or metastatic malignant neoplasm that affects the testis. "Among 25 hub genes, EFTUD2, HNRNPD, KIT, NCL and RPS8 were significantly upregulated in testicular cancer patients, however, ELAVL2 and NRXN1 were significantly downregulated using GEPIA online database." (PMID 33746583, 2021). "As expected, EFTUD2, ELAVL2, HNRNPD, KIT, NCL, NRXN1 and RPS8 were significantly varied in testicular cancer patients." (PMID 33746583, 2021).